PGR (progesterone receptor)
Description:
The steroid hormones and their receptors are involved in the regulation of eukaryotic gene expression and affect cellular proliferation and differentiation in target tissues. Depending on the isoform, progesterone receptor functions as a transcriptional activator or repressor. [Isoform A]: Ligand-dependent transdominant repressor of steroid hormone receptor transcriptional activity including repression of its isoform B, MR and ER. Transrepressional activity may involve recruitment of corepressor NCOR2. [Isoform B]: Transcriptional activator of several progesteron-dependent promoters in a variety of cell types. Involved in activation of SRC-dependent MAPK signaling on hormone stimulation. [Isoform 4]: Increases mitochondrial membrane potential and cellular respiration upon stimulation by progesterone.
Synonyms: PR; NR3C3
Tractability: Small molecule: an approved drug acts on it; a structure with a bound ligand is known; a high-quality ligand is known; it has a high-quality binding pocket; it belongs to a druggable protein family. Antibody: its Gene Ontology location is reachable by antibodies, with high confidence. PROTAC: UniProt records ubiquitination sites on it; ubiquitination databases record sites on it; a small molecule that binds it is known.
Target class: Transcription factor; Nuclear hormone receptor subfamily 3; Nuclear receptor; Nuclear hormone receptor subfamily 3 group C; Nuclear hormone receptor subfamily 3 group C member 3
Chemical probes: CHEMBL117465, CHEMBL1672547, CHEMBL522432, LECANINDOLE D, PD083060
Safety:
Unwanted effects reported when the protein is acted on. In parentheses: how it was acted on, where the effect was seen, and who reports it.
Contraceptive (inhibition; reproductive; source: Brennan et al. (2024))
Emergency contraceptives (activation; reproductive; source: Brennan et al. (2024))
induction of medical abortion (activation; reproductive; source: Brennan et al. (2024))
Gene: Protein-coding gene on chromosome 11 (101,029,624 to 101,129,813, reverse strand). Ensembl gene ENSG00000082175.
Subcellular location: Nucleus; Cytoplasm; Nucleus (Isoform A); Mitochondrion outer membrane (Isoform 4)
Pathways (Reactome):
Developmental Biology: Developmental Lineage of Mammary Gland Alveolar Cells; Developmental Lineage of Mammary Gland Luminal Epithelial Cells
Signal Transduction: Estrogen-dependent gene expression; Nuclear signaling by ERBB4
Cellular responses to stimuli: HSP90 chaperone cycle for steroid hormone receptors (SHR) in the presence of ligand
Gene expression (Transcription): Nuclear Receptor transcription pathway
Metabolism of proteins: SUMOylation of intracellular receptors
Gene Ontology:
Molecular function: ATPase binding; DNA-binding transcription activator activity, RNA polymerase II-specific; enzyme binding; identical protein binding; nuclear receptor activity; protein binding; RNA polymerase II cis-regulatory region sequence-specific DNA binding; transcription coactivator binding; DNA binding; DNA-binding transcription factor activity, RNA polymerase II-specific; estrogen response element binding; nuclear steroid receptor activity; DNA-binding transcription factor activity; sequence-specific DNA binding; sequence-specific double-stranded DNA binding; steroid binding; zinc ion binding
Biological process: maintenance of protein location in nucleus; negative regulation of gene expression; negative regulation of phosphorylation; positive regulation of transcription by RNA polymerase II; progesterone receptor signaling pathway; regulation of DNA-templated transcription; cell-cell signaling; nuclear receptor-mediated steroid hormone signaling pathway; positive regulation of gene expression; regulation of transcription by RNA polymerase II; signal transduction; steroid hormone receptor signaling pathway
Cellular component: chromatin; plasma membrane; cytosol; nucleoplasm; nucleus; cytoplasm; mitochondrial outer membrane
Genetic constraint (gnomAD): Loss-of-function variants: 20 observed, 52.46 expected, observed/expected ratio (o/e) 0.38, 90% interval 0.27 to 0.55. The synonymous counts are far from expectation, so gnomAD's model fits this gene poorly and the ratio says little. Missense variants: 1,113 observed, 1,036.2 expected, observed/expected ratio (o/e) 1.07, 90% interval 1.02 to 1.13. Synonymous variants: 548 observed, 463.89 expected, observed/expected ratio (o/e) 1.18, 90% interval 1.1 to 1.27.
Homologues: Orthologues: chimpanzee PGR (98% identical), macaque PGR (97% identical), rabbit PGR (88% identical), pig PGR (86% identical), rat Pgr (81% identical), mouse Pgr (80% identical), dog PGR (77% identical), tropical clawed frog pgr (41% identical), zebrafish pgr (29% identical), Drosophila melanogaster ERR (11% identical). Paralogues in human: NR3C2 (31% identical), AR (27% identical), NR3C1 (26% identical), ESR1 (14% identical), ESR2 (14% identical), ESRRG (13% identical), ESRRB (13% identical), ESRRA (13% identical).
Diseases named in the same sentence as PGR in open-access papers:
PGR is named in the same sentence as 346 diseases in open-access papers, as found by Europe PMC text mining. Sharing a sentence is not in itself a finding about the gene and the disease. The quoted sentences say what the papers report.
breast cancer (3,854 papers, 1982 to 2026). A primary or metastatic malignant neoplasm involving the breast. "Elevated ZBTB16 expression has been linked to more favorable prognoses in luminal A breast cancers, where it correlates with higher estrogen and progesterone receptor expression." (PMID 41516402, 2026). "Receptor conversion occurred mainly as loss of PgR or ER expression, hence leading to breast cancer group with worse prognosis." (PMID 41511682, 2026). "The results revealed that HER2 was significantly associated with estrogen receptor status, progesterone receptor status, N stage, American Joint Committee on Cancer stage, mutation count and tumor mutation burden of breast cancer." (PMID 41383978, 2026). "Conversely, the breast cancer risk-reducing selective progesterone receptor modulator mifepristone significantly reduced cancer-related clocks in the breast compared to pre-treatment in a paired sample analysis." (PMID 40175686, 2025). "PGR, which encodes the progesterone receptor and is crucial for prognosticating hormone treatment outcomes in breast cancer, is also significant here and is closely linked to luminal breast cancer." (PMID 40709098, 2025). "The literature data indicate that the reduction of CK19 expression in breast cancer is associated with the loss of estrogen and progesterone receptor expression." (PMID 39859370, 2025). "Some important mutations in breast cancers are ER, progesterone receptor (PR), and human epithelial growth factor receptor 1/2 (HER1/2) mutations, which can affect the behavior of cancer and its treatment options." (PMID 38893257, 2024). "AR expression is associated with favorable prognostic factors of breast cancer such as lower histologic grade, ER, and PgR expression." (PMID 39497884, 2024). "Immunohistochemistry has revealed a positive relationship between the ER and proteins that have ERE in their encoded gene promoters, such as EBAG9, cyclin D1, and PgR in breast cancer." (PMID 39246627, 2024). "We then stratified patients by breast cancer subtype, high-risk estrogen receptor (ER), and/or progesterone receptor (PgR)-positive/human epidermal growth factor receptor 2 (HER2)-negative versus triple-negative breast cancer (TNBC)." (PMID 39362991, 2024). "Markers of breast cancer survival, such as estrogen receptors (ERs), progesterone receptor (PRs), and Ki67 status, are also linked to a high MBD." (PMID 39518350, 2024). "For instance, one study concluded that weight gain increases the risk of breast cancer, yet another study suggested that the effect of weight gain on breast cancer varies depending on different oestrogen and progesterone receptor statuses." (PMID 38547495, 2024). "Examples of failure to control for other cancer risk factors include the failure to record estrogen or progesterone receptor positivity, family history of cancer, prior radiation, family history of breast cancer, postmenopausal hormone use, or smoking history." (PMID 39123381, 2024). "Associations between reproductive factors and risk of breast cancer differ by subtype defined by joint estrogen receptor (ER), progesterone receptor (PR), and HER2 expression status." (PMID 38822357, 2024). "Epidermal growth factor receptor (EGFR), HER2, progesterone receptor (PR), Ki-67, PD-L1 and survivin are important gene markers associated with breast cancer." (PMID 37511584, 2023). "High expression of both CENPE and CENPF was associated with low oestrogen and progesterone receptor expression levels in breast cancer." (PMID 37592220, 2023). "Breast cancer is divided into subtypes based on the presence or loss of the expression of estrogen receptor (ER), progesterone receptor (PR), and human epidermal growth factor receptor 2 (HER2)." (PMID 37108425, 2023). "Analysis of TRIP6 expression in 95 breast cancer samples revealed associations of the TRIP6 mRNA expression level with progesterone receptor positivity and premenopausal status." (PMID 36833223, 2023).
breast cancer (continued). "The progesterone receptor is another breast cancer-relevant nuclear receptor and has been linked to CCM as well." (PMID 37019926, 2023). "Breast cancer is hormone-dependent; endocrine therapy in patients with estrogen receptor (ER) and progesterone receptor (PR) positive breast malignancies can reduce the risk for breast cancer recurrence and metastasis." (PMID 36531979, 2022). "More recently, IRS1 has also been implicated in progesterone receptor (PR)-driven stemness and endocrine resistance in ER+ breast cancer." (PMID 35846378, 2022). "CK5 and CK6 expressions were both linked to high grade, estrogen receptor, and progesterone receptor negativity in breast cancer (p < 0.0001 each), grade/stage progression in urothelial cancer (p < 0.0001), and RAS mutations in colorectal cancer (p < 0.01)." (PMID 34559291, 2022). "Adult weight gain and weight gain prior to cancer diagnosis also increase breast cancer risk and mortality, particularly for ER + and/or progesterone receptor positive (PR +) tumors." (PMID 35725493, 2022). "Triple-negative breast cancer is a sub-type of breast cancer defined by the lack of expression of the three principal biomarkers associated with breast cancer: oestrogen receptor-α, progesterone receptor and human epidermal growth factor receptor 2 (HER2)." (PMID 35323718, 2022). "A number of studies have reported associations between PGR gene variants and hormone-related disorders, including breast cancer, where PGR gene mutation more frequently affects ER-positive breast cancer." (PMID 36585729, 2022). "We conducted a systematic review and meta-analysis to investigate the effect of oral contraceptives (OCs) on risk of breast cancer (BrCa) by status of estrogen receptor (ER), progesterone receptor (PR), and human epidermal growth factor receptor 2 (HER2)." (PMID 35158842, 2022). "BRCA‐associated breast cancers had less progesterone receptor expression, higher nuclear grade, and higher Oncotype DX Breast Recurrence Scores® with median Recurrence Score® 29, compared to 16 in cancers without mutations (p < 0.0001)." (PMID 35128817, 2022). "Association of pHER2 and hormone receptors (ER and PgR) family members with clinicopathological prognostic features of breast cancer (BC) patients." (PMID 35505646, 2022). "The minor allele frequency of PGR rs1042838 was significantly higher in breast cancer patients compared to controls." (PMID 35160095, 2022). "Based on the underlying molecular markers, multiple types of breast cancer are identified, namely ER (estrogen receptor), PR (progesterone receptor) and HER2 (epidermal growth factor receptor 2)." (PMID 33417986, 2021). "Clinically used breast cancer markers, such as tumor size, tumor grade, progesterone receptor (PR) status, and Ki-67 status, are known to be associated with short-term survival, but the association of these markers with long-term (25-year) survival is unclear." (PMID 34190995, 2021). "The prognosis of breast cancer depends on several characteristic features, namely, estrogen receptor (ER), progesterone receptor (PR), and HER2 receptor expression and mutation status." (PMID 33412559, 2021). "For premenopausal women, obesity has a protective effect on hormone receptor-positive breast cancer but increases the risk of estrogen receptor (ER)+/progesterone receptor (PR)- and ER-/PR- breast cancer." (PMID 33842335, 2021). "High body weight was also associated with more progesterone receptor-positive breast cancer and estrogen receptor-positive breast cancer." (PMID 34684657, 2021).
breast cancer (continued). "Its expression is higher in luminal type A breast cancer than other aggressive breast cancer subtypes and studies have demonstrated that progesterone receptor-positive (PR+) breast cancers are associated with better prognosis." (PMID 34172056, 2021). "Triple-negative breast cancer (TNBC) is the most aggressive subtype of breast cancer that is characterized by a deficiency in the estrogen receptor (ER), progesterone receptor (PR), and human epidermal growth factor receptor 2 (HER2)." (PMID 33472170, 2021). "AIs are also increasingly used for the treatment of postmenopausal patients with estrogen/progesterone receptor-positive breast cancer, in subsequent metastatic settings, and as a tool of chemoprevention in women at increased risk of breast cancer." (PMID 34198684, 2021). "The authors found that the aberrant expression of miR-214 and miR-218 were negatively associated with Ki 67, and the expression of miR-218 expression was positively associated with progesterone receptor (PR) in breast cancer tissues." (PMID 33414456, 2021). "In breast cancer, the expression of NSUN2was significantly associated with the clinical stage, tumor type, pathological differentiation, estrogen receptor, progesterone receptor, and Ki-67 expression levels." (PMID 34195072, 2021). "For example, it is well established that parity reduces the risk for estrogen receptor- and progesterone receptor-positive breast cancers and ovarian cancer, but increases the risk of dental disease and dementia." (PMID 34176489, 2021). "In the diagnostic practice for breast cancer, immunostaining for ER, PgR, HER2, and Ki-67 is consistently requested." (PMID 34203756, 2021). "Hormonal contraception exposes women to synthetic progesterone receptor (PR) agonists, progestins, and transiently increases breast cancer risk." (PMID 34042278, 2021). "This study was aimed to determine the correlation of the risk of bone metastases in breast cancer based on the expressions of molecular markers: estrogen receptor (ER), progesterone receptor (PR), human epidermal growth factor receptor-2 (HER-2) and Ki-67." (PMID 34257962, 2021). "We examined exposure to SHS from parents during childhood and breast-cancer risk overall and by oestrogen- and progesterone-receptor status in the Norwegian Women and Cancer Study." (PMID 34999865, 2021). "Oestrogen receptor and progesterone receptor-positive breast cancers are typically associated with higher survival rates than triple-negative breast cancer." (PMID 35950182, 2021). "Are clinically used markers of breast cancer, such as tumor size, tumor grade, progesterone receptor status, and Ki-67 status, independently associated with 25-year survival and tamoxifen treatment benefit among patients with breast cancer?" (PMID 34190995, 2021). "Associations between anthropometric factors and breast cancer (BC) risk have varied inconsistently by estrogen and/or progesterone receptor (ER/PR) status." (PMID 33128203, 2021). "In one study, basal-like breast carcinomas were found to bear a higher expression of P-gp associated with the reduction or loss of estrogen receptor, progesterone receptor, and HER2." (PMID 33801360, 2021). "Conversely, NCS‐1 expression is negatively correlated to FOXA1, ESR1, and PGR, which are more commonly associated with the breast cancer luminal subtype." (PMID 31647602, 2020). "The importance of PgR expression has been reported to have strong prognostic significance in studies involving younger breast cancer patients and is linked to risk of relapse and poor survival." (PMID 32726924, 2020).